ANGPTL4 (angiopoietin like 4)
Diseases named in the same sentence as ANGPTL4 in open-access papers (continued):
Sharing a sentence is not in itself a finding about the gene and the disease.
Hypercholesterolemia (5 papers, 2015 to 2024). An increased concentration of cholesterol in the blood. "Additionally, ANGPTL4 p.Cys80fs was associated with a decreased risk of two T2D-related outcomes and a lowered probability of statin prescription and hypercholesterolaemia diagnosis." (PMID 38895109, 2024). "We also found altered DNA methylation in patients with hypercholesterolemia, in key genes associated with fatty acid transport and metabolism (hypomethylated: PPARD, PPARG, SLC27A1, SLC27A3 and SLC25A20, and hypermethylated: ANGPTL4, ACLS6, ACADM and CPT1A)." (PMID 33028190, 2020). "In our study, hypermethylation of promoters of key genes regulating cholesterol metabolism such as PCSK9, LRP1, ABCG1, ANGPTL4, SREBF1 and NR1H2, were found in obese patients with hypercholesterolemia." (PMID 33028190, 2020).
influenza (5 papers, 2019 to 2024). An acute viral infection of the respiratory tract, occurring in isolated cases, in epidemics, or in pandemics; it is caused by serologically different strains of viruses (influenzaviruses) designated A, B, and C, has a 3-day incubation period, and usually lasts for 3 to 10 days. "It has been reported that ANGPTL4 was upregulated in lung tissue samples from patients during influenza pandemics in 2009." (PMID 36009579, 2022). "Influenza infection triggers the expression of ANGPTL4 through signal transducer and activator transcription 3 (STAT3)-dependent mechanisms, leading to the exacerbation of lung inflammation and injury." (PMID 36009579, 2022). "High-throughput RNA sequencing of lung tissue samples from patients during the 1918 and 2009 influenza pandemics revealed that the angiopoietin-like 4 protein (ANGPTL4) was one of the most significantly upregulated mRNAs." (PMID 31164474, 2019). "Therefore, anti-ANGPTL4 neutralizing antibodies may improve tissue integrity and recovery from influenza and pneumococcal pneumonia." (PMID 36009579, 2022).
lipid metabolism disorders (5 papers, 2021 to 2025). "Similar conclusions were shown in this study, and we found lipid metabolism related genes, including Angptl4, Mrap, Angptl8, and C1qtnf3, were significantly changed by disruption, suggesting that disruption induced lipid metabolism disorders in the myocardium." (PMID 33842566, 2021). "However, previous studies have shown that ANGPTL4 knockout leads to severe acute phase reactions, which challenge the safety of targeting ANGPTL4 in the treatment of glucose and lipid metabolism disorders." (PMID 34582711, 2021). "Chronic intermittent hypoxia (CIH) induced lipid metabolism disorder has been reported in several studies, most of which mainly focused on the regulation of two important genes, PPARA and ANGPTL4." (PMID 36153524, 2022).
metastatic disease (5 papers, 2015 to 2025). "Analysis discovered a number of genes previously identified as playing important roles in metastatic disease (e.g., Tpx2, Angptl4, Ezr, Txnip), indicating this strategy is capable of identifying putative metastasis genes on a genome-wide scale." (PMID 27074153, 2016). "In a study of several epithelial tumor types, ANGPTL4 levels increased as tumors progressed from local to metastatic disease." (PMID 25955030, 2015). "We further expand on this point by showing that ANGPTL4 is more positively correlated to TGF-B response in metastatic tumors in general when compared to primary tumors, highlighting the TGF-b/ANGPTL4 relationship in metastatic tumors." (PMID 40233044, 2025). "In metastatic tumors, pathway and TF analyses revealed strong hypoxia-inducible factor-1α–driven hypoxia activation, influencing glycolysis (SLC2A1, SLC2A3, PGK1, PDK1, PGM1, and ALDOA), angiogenesis (ANGPTL4 and ADM), and survival in low oxygen (BNIP3, BNIP3L, and NDRG1)." (PMID 40736012, 2025).
oral cancer (5 papers, 2015 to 2025). "Based on tumor clinicopathology, high ANGPTL4 expression is associated with increased oral cancer incidence and poor prognosis." (PMID 34331381, 2021). "ANGPTL4 is a secreted matricellular protein that is broadly expressed in many types of malignant tumor and is associated with poor prognosis in oral cancer." (PMID 25999348, 2015). "ANGPTL4 expression was linked to worse OS in GIT (HR = 1.26, 95% CI: 0.94–1.69) and Oral cancers (HR = 1.54, 95% CI: 0.60–3.92), however both subgroups did not achieve statistical significance." (PMID 40233044, 2025). "ANGPTL4 seems to have a role in the metastatic process in oral cancer." (PMID 29389861, 2018).
preeclampsia (5 papers, 2017 to 2023). Preeclampsia is a hypertensive disorder of pregnancy that is characterized by new-onset hypertension with proteinuria presenting after 20 weeks of gestation, and depending on mild or severe forms may initially present with severe headache, visual disturbances, and hyperreflexia. "However, the exact mechanisms establishing the association between ANGPTL4, and preeclampsia remains a mystery." (PMID 36016656, 2022). "Interestingly, previous studies have found that ANGPTL4 is reduced in placental tissues of patients with preeclampsia, suggesting that ANGPTL4 plays an important protective role during embryo development." (PMID 32745373, 2020). "However, the function of ANGPTL4 in preeclampsia has not been studied." (PMID 29193797, 2018).
renal carcinoma (5 papers, 2005 to 2024). A carcinoma arising from the epithelium of the renal parenchyma or the renal pelvis. "Overall, we suggested that tumor angiogenesis in renal cancer cell could be inhibited by SLC39A1 through downregulating ANGPTL4, and inactivated PPAR signal pathway was the underlying mechanism." (PMID 36407113, 2022). "Analysis of TCGA pan cancer data showed that renal cancer has the highest expression of ANGPTL4 compared to 16 other solid cancers." (PMID 39105498, 2024). "In addition to HIF-1α, however, ANGPTL4 had also been confirmed as a conventional hypoxia-driven proangiogenic factor in renal cancer cells and this process could induced by PPAR signal pathway." (PMID 36407113, 2022). "In human cells, HDAC3 mediates a NCOR-dependent transcriptional repression of the ANGPTL4 gene, as shown by using a renal cancer cell line, while additional investigations are needed to unveil the potential role of HDAC in regulating ANGPTL4 expression in skeletal muscle." (PMID 35250605, 2022). "ANGPTL4's angiogenic action has been reported to be independent of VEGF in a renal carcinoma model." (PMID 15836779, 2005).
Sepsis (5 papers, 2024 to 2025). Sepsis is defined as life-threatening organ dysfunction caused by a dysregulated host response to infection. "These diverse mechanisms position Angptl4 as a promising therapeutic candidate for addressing both the vascular and inflammatory-metabolic components of sepsis-associated lung injury." (PMID 40743234, 2025). "Recent evidence indicates that ANGPTL4 may influence inflammatory responses and endothelial barrier integrity; however, its cell-specific regulatory mechanisms in sepsis-associated ALI are not well understood." (PMID 40743234, 2025). "In this study, we sought to elucidate the role of Angptl4 in sepsis-associated acute lung injury (ALI) and to systematically elucidate its synergistic effect through multiple mechanisms, including anti-inflammation, endothelial barrier stabilization, metabolic regulation, and antioxidants." (PMID 40743234, 2025). "Future research should focus on precisely elucidating the molecular mechanisms of Angptl4 and investigating its clinical applications in the treatment of sepsis and acute lung injury (ALI)." (PMID 40743234, 2025). "Animal models of sepsis and mechanical ventilation-induced acute lung injury are being used to investigate ANGPTL4’s role, but its precise impact on acute lung injury development is still not fully understood." (PMID 40743234, 2025). "Another proposed molecular mechanism of ANGPTL4 is its ability to activate the NF-κB inflammatory pathway and affect M1 macrophage polarization and pyroptosis in sepsis-related acute lung injury." (PMID 40006981, 2025). "By utilizing the Cistrome DB database, 58 potential transcription factors for Angptl4 were identified and visualized with Cytoscape to create a regulatory network related to sepsis-induced acute lung injury." (PMID 40743234, 2025). "Clinical studies have found that lower serum Angptl4 levels in sepsis patients correlate with increased disease severity and lung injury, suggesting its potential as an early diagnostic or prognostic biomarker." (PMID 40743234, 2025). "We utilized RNA-seq and bioinformatics to study Angptl4 expression and identify dysregulated genes in a mouse model of sepsis-induced acute lung injury." (PMID 40743234, 2025). "This study makes significant contributions by establishing a new link between Angptl4’s metabolic regulation and the immune-inflammatory response, thereby unveiling the complex interplay between metabolic disorders and organ damage in sepsis." (PMID 40743234, 2025). "Among them, Angptl4 has been reported to promote ferroptosis and autophagy, and knockdown of Angptl4 can inhibit sepsis-induced acute lung injury." (PMID 38842666, 2024). "Angptl4 knockdown attenuated sepsis-induced lung injury through blocking the activation of the NF-κB pathway and hindering macrophage M1 polarization." (PMID 38842666, 2024). "In conclusion, Mir22hg was able to recruit the m6A reader YTHDC1 to stabilize Angptl4 mRNA expression, thereby promoting ferritinophagy to accelerate sepsis progression." (PMID 38842666, 2024). "Its clinical significance is underscored by studies linking plasma ANGPTL4 levels to sepsis-related lung injury, where it may reduce inflammation." (PMID 40743234, 2025). "Additionally, angiopoietin-like 4 (ANGPTL4) was found to regulate STAT3 expression in immature mouse MKs during sepsis and also to promote platelet overproduction." (PMID 40710306, 2025). "Additionally, in vitro experiments confirmed the Angptl4 gene expression level in sepsis-induced acute lung injury." (PMID 40743234, 2025). "Microarray identification revealed that Angptl4 may be a potential target gene for the treatment of burn sepsis." (PMID 38842666, 2024). "However, it remains uncertain if Angptl4 affects vascular permeability and tight junction proteins in sepsis-related lung injury.the exact mechanisms and pathways involved remain unclear." (PMID 40743234, 2025).
Sepsis (continued). "The intersection of databases RM2Target, GSE179554-6 h, and GSE179554-12 h presented 7 genes (Mt1, Mt2, Alpl, Angptl4, Apod, Slc7a5, and Timp1) that may bind towards YTHDC1 in sepsis." (PMID 38842666, 2024). "Mir22hg contributed to in ferritinophagy-mediated ferroptosis in sepsis via recruiting the m6A reader YTHDC1 and strengthening Angptl4 mRNA stability, highlighting that Mir22hg may be a potential target for sepsis treatment based on ferroptosis." (PMID 38842666, 2024).
steatosis (5 papers, 2018 to 2025). Increased lipid within the cytoplasm of cells. "Notwithstanding, ANGPTL4 has also been earlier proposed as a biomarker for drug-induced steatosis." (PMID 35269515, 2022). "Based on these studies, while ANGPTL4 downregulation in the liver of LPTENKO mice could be expected to restrain steatosis, these mice still display an aberrant accumulation of lipids in hepatocytes probably because PTEN-deficiency overcomes this potential protective effect of ANGPTL4 depletion." (PMID 35409319, 2022). "Collectively, these findings implicate glycemic status, rather than steatosis per se, better explains interindividual variation in circulating ANGPTL4." (PMID 41226996, 2025).
viral infection (5 papers, 2013 to 2025). "Genes that had higher upregulation in the single-virus infections were predominantly increased late (days 4 and/or 6) and included genes associated with inflammation (Angptl4) or pulmonary fibrosis (Fosl2, Pappa, and Sphk1)." (PMID 34160242, 2021). "After the virus infection and culturing of cells in G418-containing media, the mRNA expression of Angptl4 was significantly decreased in LN229-vIII cells as measured by real time PCR analysis, while the growth ratio of the cells was not significantly altered." (PMID 23617883, 2013). "It is worth noting that genes relating to innate immune response to viral infection (e.g., DHX58, MX1, IFITM-like), cell structure integrity (e.g., ANGPTL3, ANGPTL4, ELFN2, COL5A3) and transcription factors (e.g., TUB) remained upregulated throughout the acute phase of infection (1–6 dpi)." (PMID 40758745, 2025). "It indicates that ANGPTL4 has the potential to serve as a CAP marker and host-directed targeted therapy whether for viral infection, bacterial infection or other pathogens." (PMID 37821811, 2023).
acute lung injury (4 papers, 2018 to 2025). A condition of lung damage that is characterized by bilateral pulmonary infiltrates (pulmonary edema) rich in neutrophils, and in the absence of clinical heart failure. "This study examined the link between Angptl4 expression and immune infiltration in acute lung injury (ALI), noting differences in plasma cell infiltration among groups." (PMID 40743234, 2025).
cardiac hypertrophy (4 papers, 2019 to 2024). "ANGPTL4 has been associated with a variety of diseases; however, the role of ANGPTL4 in cardiac hypertrophy remains poorly understood." (PMID 29339422, 2019). "We further demonstrated that diastolic dysfunction and cardiac hypertrophy could be prevented in HFpEF mice by administration of recombinant ANGPTL4, which was also associated with reduced collagen IV deposition." (PMID 39311911, 2024). "Thus, in our present study, we aimed to discover the effects of ANGPTL4 on cardiac hypertrophy and explore the underlying mechanism." (PMID 29339422, 2019). "We discovered that the protein expression level of ANGPTL4 is increased at the onset of pressure overload- or PE-induced cardiac hypertrophy and declines over time." (PMID 29339422, 2019). "To further evaluate the inhibitory effect of ANGPTL4 on cardiac hypertrophy, we examined the effect of exogenous ANGPTL4 on cardiac hypertrophy." (PMID 29339422, 2019). "These evidence indicate that ANGPTL4 may be effective in inhibiting cardiac hypertrophy via the regulation of PPARα." (PMID 29339422, 2019). "To confirm our hypothesis, we first determined how ANGPTL4 expression is changed in cardiac hypertrophy." (PMID 29339422, 2019). "Consistent with our previous studies, we discovered that PPARα expression is decreased in cardiomyocytes transfected with si-ANGPTL4 under PE stress, which suggested that PPARα could be one of the targets of ANGPTL4 in the regulation of cardiac hypertrophy." (PMID 29339422, 2019). "As FAO is one of the pivotal mechanisms involved in the development of cardiac hypertrophy, we explored whether ANGPTL4 affected fatty acid metabolism in hypertrophic cardiomyocytes." (PMID 29339422, 2019). "In addition, ANGPTL4 also attenuates cardiac hypertrophy with increasing PPAR-α expression." (PMID 37051105, 2023). "Therefore, our data suggest that changes in ANGPTL4 expression might play a role in the process of AB- or PE-induced cardiac hypertrophy." (PMID 29339422, 2019). "Therefore, based on the effect of ANGPTL4 on energy metabolism, we speculated that ANGPTL4 might participate in the regulation of cardiac hypertrophy." (PMID 29339422, 2019). "However, whether ANGPTL4 can regulate cardiac hypertrophy remains poorly understood." (PMID 29339422, 2019).
cholangiocarcinoma (4 papers, 2019 to 2023). A carcinoma that arises from the intrahepatic biliary tree (intrahepatic cholangiocarcinoma) or from the junction, or adjacent to the junction, of the right and left hepatic ducts (hilar cholangiocarcinoma). "Similarly, PVT1 could bind epigenetic modification complexes (PRC2) for histone methylation in the promoter of ANGPTL4, and thus, promote the malignancy of Cholangiocarcinoma." (PMID 31335317, 2019).
Clear Cell Renal Cell Carcinoma (4 papers, 2010 to 2024). "Our data indicate angiopoietin-like 4 (ANGPTL4) acts as a tumor suppressor in clear cell renal cell carcinoma via regulating lipid metabolism and identifies a cohort of patients with lower expression of ANGPTL4 that are correlated with shorter survival." (PMID 39105498, 2024).
colon adenocarcinoma (4 papers, 2021 to 2025). "Previous studies have shown ANGPTL4, through its regulation by short chain fatty acid and peroxisome proliferator-activated receptor γ (PPARγ), may play a role in the progression of colon adenocarcinoma." (PMID 39811640, 2025). "The transcription and secretion of ANGPTL4 is extremely stimulated by physiological concentrations of SCFA, as they play a role in activation of the nuclear receptor–peroxisome proliferator activated receptor ɤ (PPARɤ) responsible for ANGPTL4 synthesis in human colon adenocarcinoma cells." (PMID 34445141, 2021). "Next, we enrolled three serial sections of a colon adenocarcinoma tissue array (BioMax, Rockville, MD, USA) to evaluate the prognostic values of CRNDE, miR-29b-3p, and ANGPTL4 in CRC tissues and found that CRC tumors expressed high CRNDE and ANGPTL4 levels but a low miR-29b-3p level." (PMID 34680556, 2021).
diabetic macular edema (4 papers, 2021 to 2025). "ANGPTL4 binds neuropilins and cooperates with VEGF to induce diabetic macular edema." (PMID 34616362, 2021).
fibrosis (4 papers, 2021 to 2025). the formation of excess fibrous connective tissue in an organ or tissue in a reparative or reactive process. "In addition to HCV-mediated IR, a recent study has also associated higher ANGPTL4 serum levels with advanced fibrosis, and disease progression to cirrhosis and HCC79." (PMID 37185283, 2023). "In recent years, ANGPTL4 has been observed to be significantly upregulated in the tissues of animal fibrosis models (including the kidneys and lungs)." (PMID 41169876, 2025). "We used ELISA and RT-qPCR to investigate ANGPTL-3 and ANGPTL-4 expression in HCV patients with characterised fibrosis throughout the natural history of hepatitis C and in long-term HCV infection in vitro, before and after DAA treatment." (PMID 34360721, 2021). "As far as ANGPTL-4 BT levels are concerned, we also detected positive correlations with fibrosis stage." (PMID 34360721, 2021). "Notably, the lowest ANGPTL-4 concentrations were recorded in acute infection and mild fibrosis, with a median of 60.1 ng/mL." (PMID 34360721, 2021). "Therefore, we determined the levels of the active TGF-β peptide in patients with mild/advanced fibrosis and cirrhosis in an effort to see whether TGF-β is the link between fibrosis and the expression patterns of ANGPTL-3 and ANGPTL-4." (PMID 34360721, 2021). "DAA treatment did not alter ANGPTL-3 levels in advanced fibrosis/cirrhosis and in HCV infection in vitro, in contrast to ANGPTL-4." (PMID 34360721, 2021).
Hyperinsulinemia (4 papers, 2012 to 2023). An increased concentration of insulin in the blood. "As a consequence we observed higher ANGPTL4 expression in the insulin-resistant compared to the insulin-sensitive group after 6 hours of hyperinsulinemia." (PMID 22471940, 2012). "To investigate whether insulin lowers ANGPTL4 expression in vivo, we extracted data from a transcriptomics dataset of adipose tissue biopsies from human subjects before and after 3 h intravenously maintained euglycemic hyperinsulinemia." (PMID 32504883, 2020). "Furthermore, differences were observed in genes contributing to fatty acid, cholesterol and triglyceride metabolism (FATP2, ELOVL6, PNPLA3, SREBF1) and in genes involved in regulating lipolysis (ANGPTL4) between the insulin-resistant and -sensitive subjects especially during hyperinsulinemia." (PMID 22471940, 2012).